NRADDP (neurotrophin receptor associated death domain, pseudogene)
Gene: Transcribed unitary pseudogene on chromosome 3 (47,011,542 to 47,013,146, forward strand). Ensembl gene ENSG00000236409.
Diseases named in the same sentence as NRADDP in open-access papers:
NRADDP is named in the same sentence as 2 diseases in open-access papers, as found by Europe PMC text mining. Sharing a sentence is not in itself a finding about the gene and the disease. The quoted sentences say what the papers report.
neuroblastoma (1 paper, 2025). Neuroblastoma (NB) is the most common solid, extracranial childhood tumor. "Although NRADDP is a pseudogene and nonfunctional in humans, its mouse ortholog, Nradd, has been shown to induce apoptosis in neuroblastoma cell lines." (PMID 41333685, 2025).
cancer (1 paper, 2022). A tumor composed of atypical neoplastic, often pleomorphic cells that invade other tissues. "Little is known about the roles of the other three pseudogenes (NRADDP, ADCY10P1, and BMS1P4) in cancer." (PMID 35712126, 2022).